MIR6879 (microRNA 6879)
Synonyms: hsa-mir-6879
Gene: MicroRNA gene on chromosome 11 (65,018,505 to 65,018,570, forward strand). Ensembl gene ENSG00000278851.
Homologues: Orthologues: chimpanzee MIR6879 (100% identical).